MTOR (mechanistic target of rapamycin kinase)
Diseases named in the same sentence as MTOR in open-access papers (continued):
Sharing a sentence is not in itself a finding about the gene and the disease.
tumor (continued). "Collectively, these results indicate that SVCT2 mediates the uptake of VC, which, subsequently, leads to the inhibition of the mTOR pathway in a ROS-dependent manner, thereby promoting autophagy and the suppression of cell size and tumor growth." (PMID 36787291, 2023). "Several investigations found that TRIM44 facilitates tumor development through activation of the AKT/mTOR signaling pathway, including phosphorylated P70S6K (also known as RPS6KB1) in several cases." (PMID 35855640, 2023). "Treatments targeting key components of tumor hypoxia signaling pathways, including mTOR, are one of the current approaches to cancer therapy." (PMID 36703877, 2023). "Rapamycin is a very well-known naturally derived mTOR inhibitor which can inhibit tumor cell proliferation and has immunosuppressive properties." (PMID 38067394, 2023). "Decreased ATP levels led to the activation of AMP-activated protein kinase (AMPK), which activates the AMPK pathway and inhibits the mammalian target of rapamycin (mTOR), therefore enhancing tumor cell death." (PMID 37686159, 2023). "Activation of the mTOR pathway in tumor cells influences immune cell metabolism by altering nutrient availability and growth factor signaling." (PMID 38075052, 2023). "The dual inhibition of the PI3K/mTOR pathway increases tumor radiosensitivity by normalizing tumor vasculature." (PMID 37049920, 2023). "For canine mammary neoplasms, both Temsirolimus and Everolmius have exhibited evidence to inhibit the mTOR pathway in vitro, leading to suppressed growth of tumor-adherent cells and spheres." (PMID 37368773, 2023). "Gas1 negatively regulates the AMPK/mTOR/p70S6K signaling axis and modulates the proliferation, metastasis and abnormal metabolism of malignant tumor cells." (PMID 36843929, 2023). "In fact, an increased activity of mTOR is a well-known mechanism promoting angiogenesis 49, and the presence of tumor neo-angiogenesis is a well-established predictive factor of response to bevacizumab 50,51." (PMID 37781086, 2023). "PSMD14 knockdown has the potential to downregulate the PI3K/Akt/mTOR pathway, which was regarded as one of the key mechanisms promoting tumor growth." (PMID 38053170, 2023). "Kaempferol also has anti-tumor properties due to its modulation of the Akt/mTOR signaling and FAK pathways." (PMID 36339598, 2022). "We recently demonstrated that combinatorial treatment with AKT and mTOR inhibitors results in reduced tumor growth and increased survival of mice after subcutaneous transplantation of EpCAM+ Huh7 cells." (PMID 35454789, 2022). "In the tumor microenvironment, deficiency of fatty acids and oxygen as well as production of IFNs upregulated viperin expression via the PI3K/AKT/mTOR/HIF-1α and JAK/STAT pathways." (PMID 36227691, 2022). "mTOR is a key regulator of tumor growth and its persistent activity has been reported to cause chemo-resistance and radio-resistance." (PMID 36267578, 2022). "At the same time, a PD-L1 blockade on tumor cells was shown to inhibit tumor cell glycolysis by inhibiting mTOR signaling and downregulating glycolysis enzymes, further contributing to superior tumor control." (PMID 35203357, 2022). "The downregulation of IFN-I signaling under tumor conditions leads to the downregulation of SOCS1, which causes the activation of the PI3K-Akt/mTOR pathway." (PMID 35013108, 2022). "Other potential therapies include inhibition of mTOR with everolimus, which has shown good results with radiographic response and tumor stabilization in a phase II trial in NF1 patients." (PMID 35599811, 2022). "Many studies have also shown that the mTOR signaling pathway can promote tumor emergence and progression by regulating tumor cell death and apoptosis." (PMID 36558112, 2022). "Blocking of the mTOR pathway then occurs, thereby inhibiting tumor growth and cellular metabolic activity." (PMID 36230352, 2022).
tumor (continued). "The PI3K/AKT/mTOR-related signaling pathway and PD-L1 expression are powerfully suppressed by miR-383-5p, which inhibits BC development and tumor-induced immunosuppression." (PMID 36313570, 2022). "Recently, accumulating studies about PI3K (phosphoinositide 3-kinases) inhibitors have enriched tumor treatment methods due to the indication of the relationship between the PI3K/Akt/mTOR pathway and drug resistance and prognosis of tumor." (PMID 36034776, 2022). "Activation of the HIF-mediated PI3K/AKT/mTOR pathway alters tumor metabolism, making malignant cells more resistant to anticancer drugs." (PMID 36568220, 2022). "Intracellular signals of tumor-intrinsic PD-1 as accomplices of malignancies are candidate strategies for combination with anti-PD-1 antibodies, such as Hippo and mTOR pathways." (PMID 35663968, 2022). "The expression levels of heparinase 1, MMP9, β-catenin, N-cadherin, and PI3K/AKT/mTOR, as well as their phosphorylation levels, which are involved in tumor progression, were reduced after treatment with Gleditsiae Spina." (PMID 35299895, 2022). "Although mTOR signaling plays several evolutionarily conserved roles, it remains one of the signaling systems most involved in the tumor process, such as cell cycle, cell proliferation, and apoptosis." (PMID 36428613, 2022). "Shau-Hsuan Li and colleagues demonstrated overexpression of phosphorylated mTOR, p70S6K, and 4EBP1 in 56% tumor tissues of ESCC patients." (PMID 35574327, 2022). "By stabilizing CDCA5 protein, TPI1 activates PI3K/AKT/mTOR pathway, thereby enhancing tumor progression and glycolysis." (PMID 35509067, 2022). "Tumor mutational burden is higher than other tumor types of SGC, and the phosphatidylinositol 3-kinase (PI3K)/AKT/mTOR pathway is the most frequently altered pathway." (PMID 36333410, 2022). "Tumor-associated pathways were enriched, such as the PI3K-Akt-mTOR signaling pathway, blood vessel development, signaling by receptor tyrosine kinases, and positive regulation of cell migration." (PMID 35874676, 2022). "Increasingly, studies have shown that the PI3K/Akt/mTOR signaling pathway is related to tumor drug resistance." (PMID 34981275, 2022). "Leucine promoted adipose tissue protein synthesis through the mTOR pathway, and adipocytes promoted OC metastasis and provided energy for rapid tumor growth." (PMID 35498541, 2022). "Mammalian target of rapamycin (mTOR) regulates cellular functions by integrating intracellular signals and signals from the tumor microenvironment (TME)." (PMID 36139669, 2022). "In particular, we found that the FAK/ERK1/2 and AKT/mTOR pathway are more active in T-LBL compared to T-ALL tumor cells." (PMID 35875136, 2022). "Conversely, in tumor cells, mTOR undergoes hyperactivation, resulting in uncontrolled proliferation and tumor growth." (PMID 35805003, 2022). "Immunohistochemical staining of mTOR signaling marker, p-S6K1, also confirmed that the tumor promoting role of FOXH1 in HA22T xenografted mouse model was dependent of mTOR activation." (PMID 35255005, 2022). "Recently, AGR2 was described to promote tumor metastasis via activation of the mTOR/AKT signaling pathway." (PMID 35962061, 2022). "In TAMs, the suppression of AKT/mTOR reduces glucose catabolism and increases tumor blood vessel development." (PMID 36483029, 2022). "The RAS/MAPK and RTK signaling pathways can promote the growth and proliferation of tumor cells, and the TSC/mTOR signaling pathway can promote tumor angiogenesis." (PMID 36142223, 2022). "Tumours with high expression of p-mTOR tend to possess a higher expression of p-S6, although this was observed with statistically significant correlation only in extent score analysis (p < 0.001) even when categorised in two categories (p = 0.001)." (PMID 35883491, 2022). "The activation of the mTOR pathway is responsible for the stimulation of tumor growth and metastasis." (PMID 35682571, 2022).
tumor (continued). "Phosphatase and TENsin homolog deleted on chromosome 10 (PTEN) is a tumor suppressor known as one of the central regulators of phosphatidylinositol-3-kinase/protein kinase B/mammalian target of rapamycin (PI3K/Akt/mTOR) pathway, involved downstream RTKs." (PMID 36001861, 2022). "Overall, our findings provide new insights into the role of RNF43_p.G659fs in tumor development and suggest therapeutic uses for PI3K/mTOR inhibitors in patients whose tumors harbor this mutation." (PMID 35676246, 2022). "Western blotting was performed to measure the PI3K/AKT/mTOR pathway protein expression in tumor tissues." (PMID 36132221, 2022). "The PI3K/AKT/mTOR signalling pathway plays an important role in fundamental cellular activities such as cellular metabolism, growth, and proliferation in many tumours." (PMID 35883139, 2022). "We have previously shown a tumor-suppressive effect for miR-615-5p in hepatocellular carcinoma by downregulating mTOR." (PMID 36203751, 2022). "Meanwhile, several classic tumor-associated signaling pathways were significantly enriched in subtype A, such as WNT, TGF-β, mTOR and MAPK signaling pathways." (PMID 36300121, 2022). "One study correlated Salmonella-induced downregulation of PD-L1 in tumor tissues to the inhibition of AKT/mTOR/p70S6K signaling pathway post treatment with Salmonella in a murine tumor model." (PMID 36605208, 2022). "Reduction of PD-L1 expression reduced mTOR activity; furthermore, PD-L1 blockade by antibody attenuated mTOR activity and glycolytic metabolism in tumor cells." (PMID 35402280, 2022). "When activated, the PI3K/AKT/mTOR signaling pathway not only modulates the translation of proteins involved in cell transformation and proliferation, but is also involved in tumor metastasis, invasion, and angiogenesis." (PMID 35311154, 2022). "The PI3K/Akt/mTOR signaling pathway plays an important role in the physiological activities of tumor cells, such as energy metabolism, cell proliferation, invasion, apoptosis, and cell cycle." (PMID 36104717, 2022). "Mechanistically, chemotherapy promotes macrophage secretion of interleukin (IL)−18, which upregulates LAT2 expression in tumor cells and consequently enhances glutamine and leucine uptake- and mTOR activity-dependent CD47 expression for tumor immune envision." (PMID 36274066, 2022). "We found a significant reduction in tumor diameter with the ATP-competitive mTOR inhibitor (Ku-0063794), as expected." (PMID 36551683, 2022). "AMPK/mTOR pathway is a vital signaling pathway in tumor development, which is not only related to cell energy metabolism, but also closely related to autophagy in cells." (PMID 35813859, 2022). "Previous studies have reported the role of the PI3K-Akt-mTOR signaling pathway in promoting tumor cell proliferation and rewiring tumor metabolism." (PMID 36177003, 2022). "Interventions in the media of cultured HCC cells such as decreased content in BCAAs or enrichment with the mTOR inhibitor rapamycin or inhibition of BCKDK result in lower tumor cell proliferation rates." (PMID 35409380, 2022). "Myc activates the PI3K/AKT/mTOR pathway in the tumor cell, leading to an increase in protein synthesis and glycolysis with final oxidative phosphorylation." (PMID 35053485, 2022). "mTOR is a serine/threonine protein kinase that controls cell division, autophagy, maturation and apoptosis through the PI3K/AKT/mTOR pathway and is also involved in tumor metastasis." (PMID 36589825, 2022). "Some studies have found that tumour cells can regulate exosomal transfer of miRNA from fibroblasts by expressing lncRNAs, and the miRNAs can further regulate PI3K/AKT/mTOR signalling to affect the tumour microenvironment." (PMID 35883139, 2022).
tumor (continued). "Third, LKB1-AMPK axis-mediated PROX1 phosphorylation results in BCAA degradation, which suppresses mTOR signalling activity and facilitates tumour cell adaptation to metabolic stresses." (PMID 36433955, 2022). "The mTOR inhibitor rapamycin found in previous studies can inhibit the prolongation of protein translation in APC-deficient tumor cells and can cause tumor cell growth stagnation." (PMID 36258178, 2022). "Some studies have illustrated that components of mTOR-related pathways can be used to predict tumor response to nCT." (PMID 36569844, 2022). "Phosphorylated AMPK can promote apoptosis and suppress the proliferation of tumor cells by inhibiting the mammalian target of rapamycin (mTOR) pathway." (PMID 35346234, 2022). "We next explored the reciprocal interactions between MAPK and mTOR signaling pathways in citrate‐induced senescent tumor cells." (PMID 34747157, 2022). "As a rapamycin analogue, ridaforolimus can effectively inhibit mTOR, thus inhibiting tumor growth and improving the progression-free survival of EC patients." (PMID 35800058, 2022). "TGF-β expressed by tumor cells stimulates the mammalian target of rapamycin (mTOR) pathway and induces the CD73 production while maintaining the stability of HIF1-α." (PMID 35836249, 2022). "This treatment reduces tumor proliferation probably due to the decrease in the activity of the mTOR downstream protein, p70S6K." (PMID 35646638, 2022). "Suppression of the PI3K-Akt-mTOR signaling pathway cannot only restrain tumor growth itself, but also modulates anti-tumor cytokine production and increase-activated CD8+ T-cell infiltration." (PMID 35646684, 2022). "Inhibition of AMPK in OR CRC cells induces tumor-suppressive autophagy through inactivation of Akt/mTOR pathway and decrease in the level of GLUT1, PFKFB3 and PFK1." (PMID 36359211, 2022). "Specifically, MTOR S1261 was also significantly expressed in the tumor tissues in EDAC (t-test, FC (tumor/normal) = 5.3, p = 0.019), which showed significantly positive association (Pearson correlation, R = 0.96, p = 2.4E-3)." (PMID 35397555, 2022). "Activity signaling cascade in HCC, including Ras/Raf/MEK/ERK and Ras/PI3K/Akt/mTOR, which promotes transcription of genes involved in tumor proliferation." (PMID 35163556, 2022). "The results showed that mTOR signaling pathway was the most enriched pathway, which was documented related to angiogenesis in tumor microenvironment." (PMID 35350778, 2022). "The phosphorylation-activated tumorigenic signal PI3K/AKT/mTOR advances the production of downstream HIF-1α to adapt to tumor hypoxia." (PMID 35413842, 2022). "One major adaptive mechanism that grants to tumor cells the capacity to survive mTOR inhibition by Rapalogs consists of the activation of the pro-survival RTK/PI3K/Akt signaling axis, due to interruption of the negative feedback emanating from mTORC1." (PMID 36077374, 2022). "PI3K/AKT/mTOR signaling pathway is a kinase pathway that promotes tumor cell proliferation and survival." (PMID 35505937, 2022). "Recent studies indicate that mTOR inhibitors, especially sirolimus, inhibit tumor development in multiple ways that are not fully understood." (PMID 35505648, 2022). "MYC usually participates in tumor metabolism in combination with other molecules and pathways, such as mTOR and HIF." (PMID 35053485, 2022). "The most common of these pathways is the phosphatidylinositol 3-kinase (PI3K)/AKT/mTOR (tumor survival pathway) and its interrelated pathways, which will be discussed in more detail later in this review." (PMID 35327484, 2022). "MLN0128 (also called INK128, sapanisertib, TAK‐228) is a pan‐mTOR inhibitor that has potent anti‐tumor effects in PIK3CA‐mutant colorectal cancer and CD44‐high HCC xenografts." (PMID 35587712, 2022). "Previous studies showed that cell-intrinsic PD-L1/PD-1 signaling promoted tumor development by activating downstream mammalian target of rapamycin (mTOR) signaling." (PMID 35464451, 2022).
tumor (continued). "Based on the pre-neoCRT tumor cell PD-L1 expression, less patients with T4b classification and lower mTOR expression were observed in the score 0 group." (PMID 35201501, 2022). "Compared with groups received pyrotinib or HDACs/mTOR inhibitor 1 monotherapy or vehicle, combination group had obviously stronger antitumor effect in CDXs and PDXs with significant reduction of tumor volume and weight." (PMID 36457011, 2022). "The mTOR and its regulation of immune response in the tumor microenvironment are discussed in more detail elsewhere." (PMID 35327484, 2022). "As a key point to tumor anabolism, mTOR is mainly activated by phosphatidylinositol-3 kinase/protein kinase B/mammalian target of rapamycin (PI3K/AKT/mTOR) signal, which also regulates HIF-1α translation." (PMID 35413842, 2022). "The mTOR pathway, which regulates tumor metabolism and promotes growth and metastasis, is activated in many cancers, including that of breast, prostate, hepatocellular, pancreatic, renal, and melanoma cancers." (PMID 35163356, 2022). "Translational data showed the target engagement of the mTOR pathway that was associated with changes in TME and proliferation of tumor cells." (PMID 36139669, 2022). "Up-regulation or over-expression of the AKT/mTOR pathway leads to tumor growth and poor prognosis by affecting autophagy." (PMID 36091810, 2022). "We found the effects of SLC6A14 on tumor cell growth in vitro and tumorigenesis in vivo, and confirmed that Akt-mTOR signaling was activated in SLC6A14-mediated CRC progression." (PMID 35907820, 2022). "A phosphoinositide 3-kinase (PI3K), Akt, and mammalian target of rapamycin (mTOR) protein inhibit cell apoptosis favoring tumor growth." (PMID 35983376, 2022). "The cascade signaling of PI3K/Akt/mTOR is a crucial key step in the cell cycle, tumor development, and survival." (PMID 36139460, 2022). "Previous studies have fully confirmed the signaling pathways involved in tumor cell progression, including mTOR, PI3K-AKT, and MAPK/ERK1/2." (PMID 34853466, 2022). "While NFκB activation generates an inflammatory microenvironment that favors tumor growth, mTOR activation increases the translation of cell survival genes (cyclin D1, Bcl-xL, and COX2)." (PMID 35900274, 2022). "tried mTOR inhibitors in combination with anti-PD-1 to accomplish more durable and synergistic tumor regression." (PMID 35663968, 2022). "Compared with inhibiting PI3K or mTOR alone, voxtalisib is far more effective in reducing the concentration-dependent reduction of viable/proliferating tumour cells." (PMID 35614940, 2022). "Oppositely, high levels of PD-L1 expression in tumor cells can activate the Akt/mTOR pathway and strengthen glycolytic process." (PMID 35920986, 2022). "Sorafenib combined with everolimus (an mTOR inhibitor) significantly reduced tumor growth and restored sensitivity to sorafenib therapy in LINC01468-overexpressing tumors." (PMID 36344496, 2022). "The patient then received the MTOR inhibitor everolimus that alleviated her symptoms but the tumor went into remission again after another 15 months." (PMID 36465390, 2022). "Previous studies have shown this intracellular signaling generally determines the triggering of MAPKs and of PI3K/Akt/mTOR pathways to take part in the progression of tumor." (PMID 36523593, 2022). "Hypoactivation of estrogen receptor (ER) and hyperactivation of Hedgehog and PI3K/AKT/mTOR signaling cascades are involved in a transition to neoplasia, while the decreased activity of androgen receptor (AR) and Wnt pathways contribute to disease progression." (PMID 36497095, 2022). "mTOR is activated in various pathological cellular processes, such as tumor formation, angiogenesis, insulin resistance, and T lymphocyte activation." (PMID 35837284, 2022). "Targeting PI3K/AKT/mTOR-mediated autophagy is not only an essential strategy for treating tumors but also plays a vital role in improving the sensitivity of tumor cells to radiotherapy and chemotherapy." (PMID 36220835, 2022).